FBXL22 (F-box and leucine rich repeat protein 22)
Description:
Substrate-recognition component of the SCF (SKP1-CUL1-F-box protein)-type E3 ubiquitin ligase complex. Promotes ubiquitination of sarcomeric proteins alpha-actinin-2 (ACTN2) and filamin-C (FLNC).
Synonyms: Fbl22; FLJ39626
Tractability: No criterion of Open Targets' tractability assessment is met for any kind of drug.
Gene: Protein-coding gene on chromosome 15 (63,597,353 to 63,602,428, forward strand). Ensembl gene ENSG00000197361.
Subcellular location: Cytoplasm, myofibril, sarcomere, Z line
Subcellular location (Human Protein Atlas): Cytosol
Pathways (Reactome):
Immune System: Antigen processing: Ubiquitination & Proteasome degradation
Metabolism of proteins: Neddylation
Gene Ontology:
Molecular function: protein binding; ubiquitin protein ligase activity
Biological process: proteasome-mediated ubiquitin-dependent protein catabolic process; SCF-dependent proteasomal ubiquitin-dependent protein catabolic process; protein ubiquitination
Cellular component: cytosol; Z disc
Genetic constraint (gnomAD): Loss-of-function variants: 12 observed, 10.79 expected, observed/expected ratio (o/e) 1.11, 90% interval 0.71 to 1.74. The upper end of that interval is the gene's LOEUF score, 1.74, which puts it in group 6 of 6, group 1 being the genes least tolerant of losing a copy. Missense variants: 398 observed, 304.21 expected, observed/expected ratio (o/e) 1.31, 90% interval 1.2 to 1.42. Synonymous variants: 158 observed, 138.7 expected, observed/expected ratio (o/e) 1.14, 90% interval 1 to 1.3.
Homologues: Orthologues: pig FBXL22 (90% identical), dog FBXL22 (87% identical), rabbit FBXL22 (87% identical), rat Fbxl22 (84% identical), mouse Fbxl22 (81% identical), chimpanzee FBXL22 (59% identical), macaque FBXL22 (57% identical), zebrafish fbxl22 (53% identical), tropical clawed frog fbxl22 (52% identical), Caenorhabditis elegans gadr-5 (26% identical), Drosophila melanogaster CG8272 (25% identical), Drosophila melanogaster CG5003 (23% identical), and 23 more. Paralogues in human: FBXL7 (26% identical), FBXL20 (25% identical), FBXL13 (24% identical), FBXL2 (24% identical), FBXL6 (23% identical), FBXL18 (22% identical), FBXL3 (21% identical), FBXL15 (21% identical), FBXL16 (21% identical), FBXL4 (19% identical), FBXL5 (19% identical), FBXL19 (16% identical), and 3 more.
Diseases named in the same sentence as FBXL22 in open-access papers:
FBXL22 is named in the same sentence as 7 diseases in open-access papers, as found by Europe PMC text mining. Sharing a sentence is not in itself a finding about the gene and the disease. The quoted sentences say what the papers report.
prostate carcinoma (2 papers, 2018 to 2022). A carcinoma that arises from epithelial cells of the prostate gland. "FBXL22 has been identified to correlated with ER- breast cancer in an exome-wide analysis; nevertheless, its specific effects on cancer, including prostate cancer, is unclear." (PMID 36103249, 2022). "FBXL22 is lowly expressed in the TCGA prostate cancer dataset (average FPKM=1.8, SD=1.2) and therefore may not be a good biomarker candidate." (PMID 29416676, 2018).
cancer (2 papers, 2021 to 2022). A tumor composed of atypical neoplastic, often pleomorphic cells that invade other tissues. "Some genes comprising CRRS have been reported to involve the malignant phenotypes in different cancers, such as CRTC2, FBXL22, OPRL1, and PSMA4." (PMID 34862329, 2021).
FBXL22 also shares sentences with these, for which no sentence is quoted: tumor (2 papers); breast carcinoma (1); muscle atrophy (1); neuroblastoma (1); scoliosis (1).